NAT10 (N-acetyltransferase 10)
Diseases named in the same sentence as NAT10 in open-access papers (continued):
Sharing a sentence is not in itself a finding about the gene and the disease.
tumor (continued). "Finally, we evaluated the therapeutic value of the NAT10 specific inhibitor-remodelin in 4NQO-induced murine OSCC tumors through tumorigenesis and found that remodelin could inhibit tumor progression." (PMID 37914704, 2023). "Interestingly, in mice treated with IgG as a control, NAT10 downregulation substantially suppressed CCa progression, while there was no discernible difference in tumor growth between the control and U14‐oeFOXP1 groups." (PMID 37818745, 2023). "However, the potential mechanisms by which NAT10 modulates tumour initiation and progression have not yet been elucidated." (PMID 36908042, 2023). "Finally, the NAT10-specific inhibitor, remodelin, could inhibit HNSCC tumorigenesis in a 4-Nitroquinoline 1-oxide (4NQO)-induced murine tumor model and remodel the tumor microenvironment, including angiogenesis, CD8+ T cells and Treg recruitment." (PMID 37914704, 2023). "Thus, NAT10 expression was significantly upregulated in HCC tumor tissues compared with their non-tumorous counterparts." (PMID 28859621, 2017). "Of note, we demonstrated that the GST N-terminal domain of CLIC3 could bind the N-acetyltransferase domain of NAT10, which indicates that CLIC3 may act as a molecular chaperone and possibly alter the spatial conformation of NAT10, thereby changing the role of NAT10 in tumor progression." (PMID 38182571, 2024). "Moreover, RNA-seq results showed that NAT10 promoted the transcription of multiple critical cytokines such as CXCL3 and CXCL8 and suppressed CXCL10, CXCL11 and so on, which are important for the recruitment of immune cells, angiogenesis, tumor microenvironment remodeling, and cancer progression." (PMID 37914704, 2023). "Therefore, consistent with the role of the NAT10/ac4C/FOXP1 axis in facilitating the upregulation of immune checkpoint genes and subsequent immune evasion, inhibition of this axis resulted in PD‐L1 blockade‐induced tumor regression that correspondingly inhibited CCa progression." (PMID 37818745, 2023). "Thereafter, further in vivo rescue experiments were conducted, and our data demonstrated that the impaired potential of in vivo tumor growth triggered by NAT10 knockout could be restored by stable MDM2 overexpression, showing that MDM2 mediates the oncogenic functions of NAT10." (PMID 36609449, 2023). "Our results suggest a significant negative correlation between NAT10 expression and CD8+ T cell infiltration around the tumor, indicating that NAT10 suppresses the cytotoxic activity of CD8+ T cells." (PMID 39648231, 2024). "The underlying reasons, on the one hand, are probably that the fate of overexpressed NAT10–THUMPD1 complex is not simply an increase in ac4C level, but other unknown biological alteration that affects tumor progression as well." (PMID 34762107, 2021). "However, NAT10 expression did not correlate significantly with age, α-fetoprotein (AFP) levels, capsular formation, tumor number, margin status and Edmondson-Steiner grade." (PMID 28859621, 2017).
cancer (118 papers, 2014 to 2026). A tumor composed of atypical neoplastic, often pleomorphic cells that invade other tissues. "Clinically, NAT10 overexpression has been associated with chemotherapy resistance, recurrence, and poor clinical prognosis in various types of cancer." (PMID 41316475, 2025). "NAT10 involvement in cancer is strongly associated with cancer initiation, proliferation, and migration." (PMID 41316475, 2025). "NAT10, responsible for catalyzing ac4C, has been implicated in multiple cancers and is thought to promote therapeutic resistance by facilitating metabolic reprogramming." (PMID 41310903, 2025). "These pathways, which are closely associated with cancer progression, strongly suggest that NAT10 promotes HCC tumorigenicity by regulating these oncogenic signaling networks." (PMID 41476650, 2025). "It has been previously reported that Remodelin, an inhibitor of NAT10, can enhance cancer cell susceptibility to therapeutic agents." (PMID 41310903, 2025). "Identifying additional combination therapies associated with NAT10 knockdown is potentially valuable for future cancer treatment methods." (PMID 39817252, 2025). "Further research is needed to comprehensively clarify the mechanisms underlying the dual role of NAT10 in cancer development and progression." (PMID 41316475, 2025). "Dysregulation or abnormal expression of NAT10 has been implicated in the development and progression of multiple pathological conditions, particularly cancer." (PMID 41408569, 2025). "Its disruption ablates ac4C modifications at specific RNA sites, and studies have shown that ac4C levels and NAT10 expression are associated with the development of various diseases, including cancers, autoimmune, cardiovascular, and inflammatory diseases." (PMID 40593466, 2025). "NAT10-mediated ac4C modification is associated with cancer progression, and inhibiting it can block cancer progression." (PMID 40588654, 2025). "Accumulating evidence indicates that upregulated NAT10 expression is associated with cancer development and metastasis." (PMID 40109769, 2025). "NAT10 has been linked to cancer and premature aging syndromes, emphasizing its potential importance in human disease pathology." (PMID 38233839, 2024). "The proliferation and survival diminish in NAT10-deficient cancer cells, prompting further investigations of the underlying mechanism behind this observation." (PMID 38233930, 2024). "NAT10 is always overexpressed in various cancers and is significantly associated with clinical features and poor prognosis." (PMID 37914704, 2023). "We confirmed that the expression levels and genomic mutation rates of NAT10 differed significantly between cancer and normal tissues." (PMID 36949954, 2023). "In our study, we elucidated the underlying mechanism by which NAT10 promotes cancer metastasis via GLMP mRNA ac4C modification, an important mechanism in stabilizing the target mRNA, to evoke oncogenic MAPK/ERK signaling." (PMID 37914704, 2023). "Accumulating evidence shows that NAT10 is predominantly localized in the nucleolus, and its mislocalization has been linked to human cancer progression." (PMID 35986334, 2022). "To confirm the reduced proliferative and survival effect in NAT10‐deficient cancer cells, we performed expression analysis of some cell proliferation genes such as BCL2, p16, and p21." (PMID 36149760, 2022). "In untargeted lipidomics, 496 out of 2 279 lipids were statistically significant in NAT10 depleted cancer cells, of which pathways associated with FA metabolism are the most enriched." (PMID 36149760, 2022). "Recently, we reported that treating cancer cells with Remodelin, a small molecule inhibitor of NAT10, causes alteration in global lipid metabolism." (PMID 36149760, 2022). "Previous results have shown that NAT10 deficiency in cancer cells causes decreased cell proliferation and cell survival." (PMID 36149760, 2022).
cancer (continued). "Gene set enrichment analysis (GSEA) was applied to determine the cancer-associated pathways with NAT10." (PMID 34362389, 2021). "Association of NAT10 with several diseases including cancer, makes it a promising therapeutic target." (PMID 33723305, 2021). "According to the COSMIC database, NAT10 is mutated in multiple cancer types." (PMID 39817252, 2025). "Genetic mutations can lead to dysregulated NAT10 expression patterns in cancer." (PMID 39817252, 2025). "Therefore, studying NAT10 mutation sites is potentially significant for increasing our understanding of cancer biology and exploring new methods for prevention and treatment." (PMID 39817252, 2025). "Additionally, other findings have shown that the expression of essential iron metabolism‒related genes, including MAP1LC3A, SLC7A11, GCLC, and SLC39A8, is significantly downregulated in NAT10-deficient cancer cells." (PMID 41316475, 2025). "NAT10 (N-acetyltransferase 10) currently stands as the sole known eukaryotic enzyme responsible for ac4C modification, with its catalyzed mRNA implicated in various human diseases, notably cancer." (PMID 39418179, 2024). "NAT10 is highly expressed and associated with poor prognosis in pan‐cancers." (PMID 39640362, 2024). "Thus, above results demonstrate that the high expression of NAT10 is associated with poor prognosis in cancers." (PMID 38308713, 2024). "Interestingly, the occurrence and development of various cancers have been recently associated with NAT10." (PMID 38233930, 2024). "Since the evidence points toward ferroptosis induction through NAT10 depletion, we then asked whether there is an elevation in fatty acids associated to ferroptosis in NAT10-depleted cancer cells." (PMID 37237981, 2023). "However, the exact roles of NAT10, specifically its ac4C-associated biological functions, in human cancers remain undefined." (PMID 36609449, 2023). "Overall, NAT10 expression is an independent risk factor for poor prognosis in these cancers." (PMID 36553667, 2022). "Overall, NAT10 depletion in cancer cells could cause complete blockage of FA metabolism, resulting in reduced cell growth and cell death." (PMID 36149760, 2022). "NAT10 depletion in cancer cells results in the dysfunction of FA metabolism, causing cell death." (PMID 36149760, 2022). "Moreover, we postulate that the degree of the cancer-promoting impact of NAT10 in CRC might be related to the mutation status of KRAS." (PMID 39905540, 2025). "In this mini review, we systematically summarize the functional roles and mechanisms of NAT10-mediated ac4C modification in both normal development and cancer." (PMID 41869016, 2026). "According to prior studies, the NAT10-mediated ac4C modification of RNA facilitates cancer cells’ adaptation to drugs or other extracellular stimuli." (PMID 39905540, 2025). "NAT10 critically promotes this survival advantage by directly bolstering the expression of key antiapoptotic regulators, allowing cancer cells to withstand both intrinsic and therapy-induced stress." (PMID 41316475, 2025). "In summary, this review clarifies the multifaceted roles of ac4C modification in both health and disease and explores NAT10‐targeted therapies with the aim of advancing cancer research and improving patient outcomes." (PMID 39764566, 2025). "NAT10 is overexpressed in many cancers, such as breast, liver, colorectal, lung, bladder, cervical, and oral cancers, as well as multiple myeloma." (PMID 41369374, 2025). "By inducing the ac4C modification and stability of epithelial-mesenchymal transition (EMT) markers, NAT10 plays a crucial role in promoting cancer metastasis." (PMID 40588654, 2025). "This dual regulatory mechanism leads NAT10 to exhibit critical oncogenic phenotypes across various cancer types." (PMID 40881352, 2025).
cancer (continued). "Studies have shown that treatment of cancer cells with Remodelin markedly reduced the levels of total cholesterol and triglycerides, indicating that NAT10 plays an important role in maintaining mitochondrial fatty acid metabolism." (PMID 41310903, 2025). "In NAT10-depleted cancer cells, the downregulation of overall lipid content, triglycerides and total cholesterol were detected." (PMID 40588654, 2025). "Through high-throughput sequencing analysis of NAT10-depleted cancer cells, fatty acid metabolism emerged as the top enriched pathway among differential downregulation genes, suggesting NAT10 plays a positive regulatory role in fatty acid metabolism." (PMID 40588654, 2025). "Encouragingly, a recent promising study discovered lead compound #7586‐3507, which can target NAT10 Khib modification and inhibit cancer metastasis." (PMID 39764566, 2025). "Overall, these discoveries emphasize the clinical importance of NAT10 in cancer and its potential as a therapeutic target and a prognostic biomarker in multiple cancer types." (PMID 41316475, 2025). "NAT10‐mediated ac4C modification can facilitate FA metabolism in cancer cells by improving the stability of FA metabolism genes." (PMID 39817252, 2025). "Regarding the role of NAT10 in promoting cancer, we conducted further studies to determine its role in promoting cancer." (PMID 41189569, 2025). "The following section dissects how NAT10 acts as both a master regulator of malignant progression and a promising pan-cancer therapeutic target." (PMID 40588654, 2025). "Recent studies reveal that aberrant N4-acetylcytidine (ac4C) modification, catalyzed by NAT10, drives cancer progression by stabilizing oncogenic mRNAs." (PMID 40999468, 2025). "This interesting study reveals the oncogenic role of NAT10‐mediated ac4C in the crosstalk between glycolysis regulation and immunosuppression in cancer cells." (PMID 39764566, 2025). "This indicates that NAT10-mediated ac4C modification is conducive to cancer occurrence and progression." (PMID 40303290, 2025). "Recent studies have identified the N-acetyltransferase 10 (NAT10), an enzyme responsible for catalyzing N4-acetylcytidine (ac4C) modification in RNA, as a key factor in cancer biology, with diverse roles across multiple cancer types." (PMID 40288646, 2025). "N-acetyltransferase 10 (NAT10), the only known ac4C “writer” protein, is a key regulator of RNA metabolism and implicated in cancer progression." (PMID 39905540, 2025). "Collectively, we provided evidence that NAT10 promotes lysosomal degradation of E‐cadherin and cancer metastasis in an ATP6V0E1‐dependent manner." (PMID 40729677, 2025). "NAT10 inhibitors also enhance the efficacy of chemotherapy and radiotherapy by disrupting the DNA repair machinery of cancer cells, which increases the accumulation of lethal DNA damage." (PMID 41316475, 2025). "The acetyltransferase NAT10, which plays a significant role in cancer biology, catalyzes this specific molecular alteration." (PMID 41310903, 2025). "NAT10 has been reported to regulate the expression of various target genes through Ac4C modification, participating in different aspects of cancer metabolism, including glucose metabolism, lipid metabolism, and amino acid metabolism." (PMID 39764566, 2025). "After NAT10 was depleted in cancer cells, lipid levels were reduced and FA metabolism was blocked, which led to cell death." (PMID 39817252, 2025). "Given the crucial role of cell death in chemoresistance in cancer, targeting NAT10 to address chemoresistance induced by ferroptosis presents a potential therapeutic strategy." (PMID 39764566, 2025). "Regulating RNA modifications has become a potential therapeutic approach for cancer, with NAT10-mediated ac4C modulation identified as a promising target for cancer treatment." (PMID 40881352, 2025). "According to recent reports, the high expression of NAT10 indicates a poor prognosis of malignant tumours." (PMID 40169553, 2025).
cancer (continued). "The present results demonstrated that the levels of ac4C and NAT10 were increased in cancer tissues and RB cell lines." (PMID 40344913, 2025). "In this review, we systematically summarized the biological activities of NAT10 and its mechanisms of action in various cancers." (PMID 39817252, 2025). "In cancer, NAT10 drives malignancy by enhancing oncogenic processes such as proliferation, metastasis, and therapy resistance, with overexpression linked to poor prognosis across multiple malignancies." (PMID 40588654, 2025). "Studies have highlighted the roles of NAT10 and ac4C modifications in various biological contexts, particularly in cancer and cardiovascular diseases." (PMID 40593466, 2025). "In multiple types of cancer, NAT10 participates in managing the expression of genes that are downstream targets through ac4C modification, impacting cancer progression and metastasis." (PMID 41316475, 2025). "In summary, NAT10 is a key factor in promoting drug resistance in various cancers by affecting target protein stability, and being involved in cell-cycle regulation and DNA repair processes." (PMID 40588654, 2025). "NAT10 has been shown to play a significant role in drug resistance across multiple types of cancers." (PMID 40588654, 2025). "Despite the growing understanding of the role of NAT10 in cancer, its specific effects on developing resistance to targeted therapies, such as EGFR-TKIs in NSCLC, remain unexplored." (PMID 41310903, 2025). "By modulating NAT10 activity or expression, researchers have achieved breakthroughs in cancer, fibrosis, neurodegeneration, and anti-aging interventions." (PMID 40588654, 2025). "Further research into NAT10 functions and expression regulation in tumors will help explore its future potential in cancer diagnosis, treatment, and prognosis." (PMID 39817252, 2025). "Studies have demonstrated that NAT10‐mediated ac4C modification regulates EMT and is closely linked to cancer invasiveness, metastasis, and treatment resistance." (PMID 39764566, 2025). "Moreover, ac4C modifications mediated by NAT10 have been implicated in the initiation and advancement of diverse cancers by influencing mRNA stability, translation efficiency, and DNA repair processes, potentially unveiling new mechanisms and therapeutic targets for cancer therapy." (PMID 39969189, 2025). "Remodelin has been used in various studies as an inhibitor of NAT10’s lysine acetyltransferase activity and is considered a potential therapeutic agent for cancer treatment." (PMID 40593466, 2025). "For example, NAT10 increases the notch receptor 3 (NOTCH3) mRNA level by improving mRNA stability via acetylation in cancers." (PMID 40226364, 2025). "Taken together, by scrutinizing the intricate mechanisms of NAT10-mediated ac4C modifications within cellular processes, researchers are uncovering hidden links between ac4C modification and cancer." (PMID 40588654, 2025). "Investigation of the upstream regulators of NAT10 helps us to better understand the mechanism of NAT10 in cancer and provides potential targets for cancer therapy." (PMID 40588654, 2025). "In summary, by fortifying the expression of antiapoptotic and ferroptosis proteins, NAT10 critically empowers cancer cells to evade programmed cell death, thereby underpinning both tumorigenesis and therapy resistance." (PMID 41316475, 2025). "NAT10 can also translocate to the cytoplasm to promote ɑ‐tubulin acetylation and enhance microtubule stability, further affecting cancer cell migration and invasion." (PMID 39817252, 2025). "NAT10 positively affects the proliferation, metastasis, invasion, and drug resistance of various cancers through the regulation of cancer‐related proteins and genes." (PMID 39817252, 2025). "Recent studies have underscored the therapeutic potential of the NAT10 inhibitor Remodelin, which can reverse drug resistance and increase apoptosis across various cancer cell types." (PMID 39905540, 2025).